KLF4 (KLF transcription factor 4)
Diseases named in the same sentence as KLF4 in open-access papers (continued):
Sharing a sentence is not in itself a finding about the gene and the disease.
osteosarcoma (continued). "To confirm that, we used immunohistochemistry to determine the expression of KLF4 in human osteosarcoma tissues and the healthy bone tissues." (PMID 27105535, 2016). "Then, we determined the effect of KLF4 on cell proliferation and tumorigenesis and found that inhibition of KLF4 expression suppressed cell growth and colony formation in human osteosarcoma cells." (PMID 27105535, 2016). "The expression of KLF4 was significantly increased in osteosarcoma tissues compared with the normal bone tissues." (PMID 27105535, 2016). "The high levels of KLF4 were involved in human osteosarcoma cell proliferation, tumorigenesis, and migration." (PMID 27105535, 2016). "The effect of KLF4 on tumor growth was further identified in nude mice with human osteosarcoma xenografts." (PMID 27105535, 2016). "Consistent with it, we also indicated CRYAB enhanced osteosarcoma cell migration and tumorigenesis and found that KLF4 promoted osteosarcoma cell migration and growth via CRYAB." (PMID 27105535, 2016). "To investigate the role of KLF4 in human osteosarcoma, we decreased KLF4 expression using shRNA in human osteosarcoma cells MG63 and SaOS2." (PMID 27105535, 2016). "In cultured and nude mouse xenografts of osteosarcoma cells, shRNA-mediated decreasing KLF4 expression inhibited cell proliferation, colony formation, and cell migration in vitro, and inhibited tumor growth, tumorigenesis in vivo." (PMID 27105535, 2016). "Here we found the expression of KLF4 was significantly increased in human osteosarcoma tissues compared with the normal tissues." (PMID 27105535, 2016). "Furthermore, treatment of osteosarcoma cells with doxorubicin activates KLF4, which promotes stemness and metastatic potential of cancer cells." (PMID 39685635, 2024). "Knockdown of KLF4 impairs the osteosarcoma CSCs and inhibits the osteosarcoma cells migration." (PMID 38561775, 2024). "Nevertheless, several authors explored the contribution of KLF4 to osteosarcoma stemness." (PMID 37176108, 2023). "It is known that KLF4 may act as an oncogene in osteosarcoma by mechanisms involving Wnt/β-catenin, Notch, and EMT, despite that it seems to not have a relevant prognostic role in some tumors." (PMID 37176108, 2023). "A binding of KLF4 with a promoter of CRYAB transactivated CRYAB expression in osteosarcoma cells." (PMID 36077137, 2022). "In osteosarcoma, KLF4 also enhanced tumorigenesis and promoted cell metastasis." (PMID 36539799, 2022). "Similarly, in osteosarcoma cells, KLF4 suppression prevented sphere formation and attenuated the levels of many stem cell-related markers, including ALDH1A1." (PMID 34680284, 2021). "Furthermore, KLF4 has been shown to activate the p38-MAPK signaling pathway in osteosarcoma cancer stem cells." (PMID 34422795, 2021). "Taken together, these data suggested KLF4 is a potential oncoprotein in human osteosarcoma." (PMID 27105535, 2016). "Moreover, we found that KLF4 enhanced osteosarcoma cell proliferation and migration via upregulating CRYAB." (PMID 27105535, 2016). "Elevated KLF4 promoted human osteosarcoma cell proliferation and metastasis." (PMID 27105535, 2016). "In addition, the clinical analysis showed that the expression level of KLF4 was increased in human osteosarcoma tissues compared with the normal bone tissues." (PMID 27105535, 2016). "Moreover, we found that KLF4 enhanced osteosarcoma cell proliferation and migration through upregulating CRYAB." (PMID 27105535, 2016). "Therefore, we speculate that SOX21-AS1 can regulate the expression of mTOR and KLF4 through sponging hsa-mir-7-5p and hsa-mir-145-5p, thereby regulating the proliferation of osteosarcoma." (PMID 34696664, 2022).
osteosarcoma (continued). "Thus, our data suggest that KLF4 may be an oncoprotein in human osteosarcoma and could be a valuable target for developing treatments for patients with osteosarcoma." (PMID 27105535, 2016). "KLF4 directly binds to the promoter to up-regulate the expression of LAMA4, which ultimately enhances the malignant behavior of osteosarcoma cells and inhibits apoptosis." (PMID 38561775, 2024). "Among them, the expression of MYH6 and SULT4A1 in osteosarcoma was higher than that in control group, while the expression of LIPE, ACTG2, KLF4, and TF was decreased." (PMID 34104648, 2021). "Whereafter, mechanistic studies indicated that KLF4 specifically bound the promoter of CRYAB and increased CRYAB expression in human osteosarcoma cells." (PMID 27105535, 2016). "After that, we analyzed the correlation between KLF4 and CRYAB in human osteosarcoma tissues and found that among 40 patient tumor tissue tested, 29 patients showed high expression of both KLF4 and CRYAB." (PMID 27105535, 2016). "Subsequently, mechanistic studies revealed KLF4 specifically bound the promoter of CRYAB and upregulated CRYAB expression in human osteosarcoma cells." (PMID 27105535, 2016). "To confirm it, we then adopted another methodology to investigate the effect of KLF4 and CRYAB on osteosarcoma tumorigenesis." (PMID 27105535, 2016). "Afterward, mechanistic studies showed KLF4 specifically bound the promoter of CRYAB and transcriptionally regulated CRYAB expression in human osteosarcoma cells." (PMID 27105535, 2016). "Therefore, our studies suggested KLF4 may be a potential target for human osteosarcoma therapy." (PMID 27105535, 2016). "However, the role of KLF4 in osteosarcoma is largely unknown." (PMID 27105535, 2016). "The expression of PDK1 was significantly upregulated in 143B OSCs rather than in 143B non-OSCs, consistent with findings in the OSC population of primary osteosarcoma specimens, along with significant upregulation of stem cell markers, such as SOX2, KLF4, and ABCG1." (PMID 40730548, 2025). "We observed that knocking out KLF4 did not decrease the viability of metastatic osteosarcoma cells grown over the course of 7 days in vitro." (PMID 37938582, 2023). "Besides these, we found KLF4, STAT3, BCL6, TFAP2A, and TFAP4 as potential drivers of osteosarcoma metastasis." (PMID 37938582, 2023). "In addition, we also found that KLF4 upregulated LAMA4 expression by directly binding to its promoter and that LINC00629 inhibited ER stress-induced apoptosis and facilitated osteosarcoma cell clonogenicity and metastasis by activating the KLF4-LAMA4 pathway." (PMID 36539799, 2022). "In addition, PBB12 interferes with the Kruppel-like factor 4 (KLF4)/hsa-miR-204-5p/activating transcription factor 2 (ATF2) pathway and affects the proliferation and invasion of osteosarcoma cells." (PMID 34141614, 2021). "Human osteosarcoma cells MG63 with or without stably knockdown KLF4 were injected subcutaneously into the groin of nude mice." (PMID 27105535, 2016). "Taken together, these data indicate that KLF4, as a transcription factor, may increase CRYAB expression in human osteosarcoma cells." (PMID 27105535, 2016). "But the reason that KLF4 was increased in human osteosarcoma tissues was still not known." (PMID 27105535, 2016). "However, the role of KLF4 in osteosarcoma was not to be reported." (PMID 27105535, 2016). "Expression of both KLF4 and CRYAB was higher in osteosarcoma tissues compared to normal bone tissues." (PMID 36077137, 2022).
ovarian carcinoma (33 papers, 2013 to 2025). A malignant neoplasm originating from the surface ovarian epithelium. "One of reasons causing this phenomenon is that KLF4 also induced cell apoptosis in ovarian cancer cells based on our unpublished data." (PMID 25137052, 2014). "KLF4 was a tumor suppressor in ovarian cancer cells by inhibiting the epithelial to mesenchymal transition." (PMID 36642729, 2023). "Overexpression of KLF4 reduced ovarian cancer cell proliferation, migration and invasion by inhibiting TGF-β-induced EMT." (PMID 37031197, 2023). "SIRT1 and KLF4 inhibit the migration and invasion of ovarian cancer cells by activating the transcription of CLDN5." (PMID 37286335, 2023). "Our results are consistent with the previously reported role of KLF-4 since we observed that DMU-214 increased KLF4 as well as IL6 transcripts level in SKOV-3 ovarian cancer cells." (PMID 32046103, 2020). "Taken together, our data revealed that circPLEKHM3 inactivates the AKT1 and canonical Wnt/β-catenin signaling pathways by regulating the expression of BRCA1, DNAJB6 and KLF4 in ovarian cancer cells." (PMID 31623606, 2019). "In ovarian tumors all patients displayed a prominent reduction of KLF4(FL) levels confirming literature on tumor-suppressive functions of KLF4 in ovarian cancer." (PMID 27323810, 2016). "When we determined the ratio KLF4α/KLF4(FL) in all these clinical samples, we noticed an appreciable increase of the ratio in 4/5 breast, 3/5 kidney, 3/5 lung, and 5/5 ovary cancer samples compared to their corresponding healthy tissues." (PMID 27323810, 2016). "Taken together, our data demonstrate that KLF4 functions as a tumor suppressor gene in ovarian cancer cells by inhibiting TGFβ-induced EMT." (PMID 25137052, 2014). "KLF4 inhibited the transforming growth factor β (TGFβ)-induced epithelial to mesenchymal transition (EMT) in ovarian cancer cells." (PMID 25137052, 2014). "KLF4 expression in SKOV3 cells led to an approximately 15-fold enrichment of E-cadherin compared to controls, indicating that KLF4 binds to the promoter of E-cadherin and activates E-cadherin expression in ovarian cancer cells." (PMID 25137052, 2014). "In summary, this is the first report showing that KLF4 functions as a tumor suppressor by inhibiting cell proliferation, migration and invasion in ovarian cancer cells through attenuating TGFβ-induced EMT." (PMID 25137052, 2014). "In this study, we investigated the role of KLF4 in ovarian cancer cells using lentiviral vector mediated inducible expression." (PMID 25137052, 2014). "To determine the role of KLF4 in ovarian cancer cells, we constructed an inducible lentiviral vector, in which the KLF4 gene was driven by tetracycline- (Tet) or a Dox-responsive promoter (TRE-tight)." (PMID 25137052, 2014). "In this study, we investigated the role of KLF4 in ovarian cancer cells by transducing the ovarian cancer cell lines SKOV3 and OVCAR3 with a doxycycline-inducible KLF4 lentiviral vector." (PMID 25137052, 2014). "Our data indicate that KLF4 transcriptionally binds to the promoters of E-cadherin, thus leading to the activation of E-cadherin expression in ovarian cancer cells." (PMID 25137052, 2014). "Overall, these studies propose that epimorphin activates αV integrin receptors and the transcription factors C/EBPβ and KLF4 which can be a positive regulator of endogenous epithelial differentiation in ovarian cancer cells." (PMID 24039787, 2013). "Besides, SIRT1 and LINC01210 downregulated KLF4, thereby promoting the proliferation, migration and invasion of ovarian cancer cells." (PMID 37031197, 2023). "Inactivation of KLF4 is frequently found in ovarian cancer patients." (PMID 37031197, 2023). "However, more evidence from mouse and human ovarian cancer cells is needed to validate the correlation between KLF4 and EOC." (PMID 37031197, 2023). "KLF4 has an inhibitory effect on ovarian cancer, but inconclusive." (PMID 37031197, 2023).
ovarian carcinoma (continued). "The signaling axis of BRCA1/DNAJB6/KLF4/AKT1 regulated ovarian cancer progression." (PMID 37031197, 2023). "Our results imply that EIF5A2 positively regulates stemness in ovarian cancer cells via E2F1/KLF4 pathway and may serve as a potential target in CSCs-targeted therapy for ovarian cancer." (PMID 33726845, 2021). "Ovarian cancer patients with higher KLF4 expression had consistently better prognoses." (PMID 31623606, 2019). "Thus, Klf4 seems to regulate Bcl-2 or Bax differently in ovarian cancer cells than in normal ovarian cells due to unidentified cellular factors." (PMID 30587813, 2018). "In addition, KLF4 was identified as a putative upstream regulator of drug resistance in ovarian cancer and together with ST3GAL5, SYNE1, CXCL8, HERC5, FOSL1, ARRDC4 merits further studies." (PMID 28473707, 2017). "For example, recent studies show that knockdown of aldehyde dehydrogenase 1 family, member A1 (ALDH1A1) in ovarian cell lines results in dramatic decrease of KLF4 and p21 protein levels, thereby leading to S and G2 phase accumulation in ovarian cancer stem-like cells." (PMID 27028863, 2016). "Altogether, these data suggest that KLF4 primarily promoted MET in ovarian cancer cells." (PMID 25137052, 2014). "Therefore, synergistically overexpression of KLF4 and inhibition of TGFβ pathway will provide a novel approach in the developing new therapeutic drugs for the treatment of ovarian cancers." (PMID 25137052, 2014). "However, the reason for KLF4 inactivation in human ovarian cancer samples is unclear." (PMID 37031197, 2023). "Therefore, the role of KLF4 as an antitumor factor in ovarian cancer needs more in-depth study." (PMID 37031197, 2023). "The anticancer activity of TSA against ovarian carcinoma cells could be mediated by the upregulation of Krüppel-like factor 4 (klf4) which plays a tumor-suppressor role in the SKOV3 cell line upon TSA treatment, and the apoptotic effect induced by TSA was enhanced by the inhibition of Akt." (PMID 36297347, 2022). "Our study not only found upregulated PFKFB3 in CSC-enriched ovarian cancer cells, but also revealed that PFKFB3 promoted clonogenicity and sphere-formation, and induced KLF4 and BMI1 expression in ovarian cancer cells." (PMID 35155224, 2022). "A significant albeit very weak correlation was detected between high expression of PFKFB3 and upregulation of KLF4 and BMI1, suggesting KLF4 and BMI1 as the potential downstream targets of PFKFB3 on CSC properties in ovarian cancer." (PMID 35155224, 2022). "Consistently, KLF4 overexpression decreased levels of vimentin and Slug and increased those of E-cadherin in OVCAR3 ovarian cancer cells." (PMID 34680284, 2021). "GEPIA further revealed a significant clinical correlation between NANOG, OCT4, KLF4, SOX9, and CD117 and HK2 expression (p < 0.05) in ovarian cancer clinical samples." (PMID 31212816, 2019). "Our current studies indicate that KLF4 inhibits TGFβ-induced EMT in both SKOV3 and OVCAR3 cells, suggesting that KLF4 attenuates the TGFβ induced EMT in ovarian cancers." (PMID 25137052, 2014). "Further experiments showed that the stemness markers including KLF4, SOX2, and CD133 were increased by IL-8 stimulation, suggesting that IL-8 secreted from CAFs may promote ovarian cancer cell stemness." (PMID 34277625, 2021). "Besides NANOG and SOX9, we also revealed an up-regulation of OCT4, KLF4, and CD117 by HK2 in ovarian cancer, which further supports the concept that HK2 regulates CSCs." (PMID 31212816, 2019). "KLF4 was reported to play a role in EMT and act as a tumor suppressor in ovarian cancer." (PMID 31623606, 2019). "Our findings demonstrated that circPLEKHM3 functions as a tumor suppressor in ovarian cancer cells by targeting the miR-9/BRCA1/DNAJB6/KLF4/AKT1 axis and may be used as a prognostic indicator and therapeutic target in ovarian cancer patients." (PMID 31623606, 2019).
ovarian carcinoma (continued). "To understand the importance of ovarian CSCs in cisplatin resistance, we initially determined the molecular characteristics of stemness and epithelial-to-mesenchymal transition (EMT)-related genes, including Klf-4, c-Met, and TCF-8, in nine ovarian cancer cell lines." (PMID 26036311, 2015). "Previous studies showed that KLF4 was downregulated in ovarian cancers compared to controls and that KLF4 did not affect cell proliferation but increased the Bcl-2/Bax ratio and inhibited apoptosis." (PMID 25137052, 2014). "There is a lack of definitive evidence whether and how KLF4 affects ovarian cancer development and progression, especially in patients." (PMID 37031197, 2023). "The role of KLF4 in ovarian cancer has not been elucidated in mechanistic detail." (PMID 25137052, 2014). "The role of KLF4 in ovarian cancer has not been adequately and mechanistically addressed." (PMID 25137052, 2014). "A previous study indicates that the expression level of KLF4 was significantly reduced in ovarian cancer compared to normal ovarian epithelium, suggesting that KLF4 might potentially act as a tumor suppressor in ovarian cancer." (PMID 25137052, 2014). "However, there are no related studies on describing the mechanism how KLF4 is involved in EMT and interacts with those pathways in ovarian cancer cells." (PMID 25137052, 2014).